COX5B (cytochrome c oxidase subunit 5B)
Description:
Component of the cytochrome c oxidase, the last enzyme in the mitochondrial electron transport chain which drives oxidative phosphorylation. The respiratory chain contains 3 multisubunit complexes succinate dehydrogenase (complex II, CII), ubiquinol-cytochrome c oxidoreductase (cytochrome b-c1 complex, complex III, CIII) and cytochrome c oxidase (complex IV, CIV), that cooperate to transfer electrons derived from NADH and succinate to molecular oxygen, creating an electrochemical gradient over the inner membrane that drives transmembrane transport and the ATP synthase. Cytochrome c oxidase is the component of the respiratory chain that catalyzes the reduction of oxygen to water. Electrons originating from reduced cytochrome c in the intermembrane space (IMS) are transferred via the dinuclear copper A center (CU(A)) of subunit 2 and heme A of subunit 1 to the active site in subunit 1, a binuclear center (BNC) formed by heme A3 and copper B (CU(B)). The BNC reduces molecular oxygen to 2 water molecules using 4 electrons from cytochrome c in the IMS and 4 protons from the mitochondrial matrix.
Synonyms: COXVB
Tractability: Small molecule: a structure with a bound ligand is known. Antibody: UniProt places it where antibodies can reach, with high confidence. PROTAC: ubiquitination databases record sites on it; its protein half-life has been measured.
Gene: Protein-coding gene on chromosome 2 (97,646,062 to 97,648,383, forward strand). Ensembl gene ENSG00000135940.
Subcellular location: Mitochondrion inner membrane
Subcellular location (Human Protein Atlas): Mitochondria; Acrosome
Pathways (Reactome):
Metabolism: Complex IV assembly; Respiratory electron transport
Cellular responses to stimuli: Cytoprotection by HMOX1
Metabolism of proteins: Mitochondrial protein degradation
Gene Ontology:
Molecular function: protein binding; cytochrome-c oxidase activity
Biological process: cellular respiration; mitochondrial electron transport, cytochrome c to oxygen; respiratory gaseous exchange by respiratory system; oxidative phosphorylation; proton transmembrane transport
Cellular component: mitochondrial inner membrane; mitochondrial membrane; mitochondrion; respiratory chain complex IV; mitochondrial envelope
Genetic constraint (gnomAD): Loss-of-function variants: 5 observed, 13.73 expected, observed/expected ratio (o/e) 0.36, 90% interval 0.19 to 0.77. The upper end of that interval is the gene's LOEUF score, 0.77, which puts it in group 3 of 6, group 1 being the genes least tolerant of losing a copy. Missense variants: 155 observed, 155.64 expected, observed/expected ratio (o/e) 1, 90% interval 0.87 to 1.14. Synonymous variants: 63 observed, 62.13 expected, observed/expected ratio (o/e) 1.01, 90% interval 0.83 to 1.25.
Homologues: Orthologues: chimpanzee COX5B (98% identical), chimpanzee COX5B (97% identical), guinea pig COX5B (88% identical), macaque COX5B (88% identical), rabbit COX5B (86% identical), dog COX5B (84% identical), mouse Cox5b (84% identical), mouse Cox5b-ps (84% identical), pig COX5B (83% identical), rat Cox5b (81% identical), zebrafish cox5ba (64% identical), zebrafish cox5bb (64% identical), and 5 more.
Diseases named in the same sentence as COX5B in open-access papers:
COX5B is named in the same sentence as 66 diseases in open-access papers, as found by Europe PMC text mining. Sharing a sentence is not in itself a finding about the gene and the disease. The quoted sentences say what the papers report.
breast cancer (11 papers, 2015 to 2025). A primary or metastatic malignant neoplasm involving the breast. "Previously, a report regarding the role of COX5B in breast cancer demonstrated that loss of COX5B function led to cell senescence." (PMID 32580279, 2020). "In this study, we first report that loss of COX5B inhibited cell proliferation and promoted cell senescence in breast cancer." (PMID 26506233, 2015). "The results showed that low COX5B expression was associated with better DFS (disease-free survival) in patients with breast cancer." (PMID 26506233, 2015). "In summary, we identified that COX5B was upregulated in breast cancer tissue and cell lines, which was associated with poor prognosis." (PMID 26506233, 2015). "However, exceptions were observed: mitochondrial tRNA translation optimization 1 (MTO1) was identified as a risk factor in breast cancer, while COX5B was associated with increased risk in endometrial cancer." (PMID 40396172, 2025). "On the other hand, COX5B expression was decreased in breast cancer, colon cancer, clear cell renal cell carcinoma (RCC), pancreatic adenocarcinoma (PAAD), head and neck cancers, glioblastoma, and liver cancer." (PMID 41502520, 2025). "As a member of COXs, COX5B has been identified as a prognostic indicator in breast cancer, clear cell renal cell carcinoma, colorectal cancer, glioma, and so on." (PMID 41502520, 2025). "The downregulation of COX5B has been reported to decrease cell proliferation and induction of senescence in breast cancer cell lines." (PMID 38612406, 2024). "COX5B has also been implicated as a predictor of clinical outcomes in the various cancer types, including HCC, breast cancer, glioma, gastric cancer, head and neck squamous cell carcinoma (HNSCC), and clear cell renal cell carcinoma (ccRCC)." (PMID 35052740, 2021). "In the literature, COX5B has also been proposed as a predictor of clinical outcomes in a various types of cancers, including breast cancer, glioma, gastric cancer, head and neck squamous cell carcinoma (HNSCC) and clear cell renal cell carcinoma (ccRCC)." (PMID 32580279, 2020). "We also utilized another online prediction tool, Oncomine, and found that COX5B expression was much higher in breast cancer tissues than in normal breast tissues." (PMID 26506233, 2015). "To assess COX5B function in breast cancer progression, we stably knocked down COX5B in 3 breast cancer cell lines (MDA-MB-231, MDA-MB-468 and MCF-7)." (PMID 26506233, 2015). "Down-regulation of COX5B in breast cancer cell lines can suppress cell proliferation and induced cell senescence which was accompanied by elevating production of IL-8 and other cytokines." (PMID 26506233, 2015). "The results showed that COX5B was significantly increased in the two breast cancer samples compared with normal tissues, which was consistent with the results of SILAC." (PMID 26506233, 2015). "Here, by performing SILAC assays in breast cancer cell models and detecting COX5B expression in tissues, we found that COX5B expression was elevated in breast cancer." (PMID 26506233, 2015). "In addition, a high expression of COX5B predicted a poor prognosis for breast cancer patients based on analyses using the Oncomine database and a Kaplan Meier plot." (PMID 26506233, 2015). "The results indicated that COX5B was upregulated in breast cancer tissues and cell lines." (PMID 26506233, 2015). "We further explore the function and mechanism of COX5B in breast cancer." (PMID 26506233, 2015). "Taken all together, our findings suggested that low COX5B expression may indicate a good prognosis for breast cancer patients." (PMID 26506233, 2015). "Interestingly, conditioned medium from COX5B knockdown cells could promote breast cancer cell migration." (PMID 26506233, 2015). "However, few studies have reported the role of COX5B in human breast cancer." (PMID 26506233, 2015).
breast cancer (continued). "UQCRFS1, COX5B, and NDUFB8 expression was blunted by both SIRT6 silencing in MDA-MB-231 cells and by the Sirt6 heterozygous deletion in mouse mammary tumors." (PMID 33482921, 2021). "COX5B has been reported as a growth-promoting gene that modulates downstream pathways in response to the induced bioenergetic alterations in HCC, breast cancer, and glioma, but its role in CRCs remains unknown." (PMID 35052740, 2021). "In this context, we developed a new Myc-based Mito-Signature consisting of 3 mitochondrial genes (HSPD1; COX5B; TIMM44) for effectively predicting tumor recurrence (HR=4.69; p=2.4e-08) and distant metastasis (HR=4.94; p=2.8e-07), in ER(+) in breast cancer patients." (PMID 29080556, 2017). "To validate the expression level of COX5B in breast cancer, we examined the expression of COX5B in two pairs of fresh, patient-derived tissue, including normal tissues, primary tumor tissues and metastatic lymph nodes." (PMID 26506233, 2015). "In addition, COX5B was also upregulated in most breast cancer cell lines than the non-malignant cell line MCF10A, both at the mRNA and protein levels." (PMID 26506233, 2015).
clear cell renal cell carcinoma (4 papers, 2020 to 2025). "Furthermore, in clear cell renal cell carcinoma, COX5B can also be identified as a prognostic factor." (PMID 36551283, 2022).
colorectal cancer (4 papers, 2017 to 2022). A primary or metastatic malignant neoplasm that affects the colon or rectum. "Similar to COX6C, COX5B was found to promote cell growth and reduce anticancer drug susceptibility in colorectal cancer cells, which may lead to unfavorable postoperative outcomes for patients with colorectal cancer." (PMID 36551283, 2022).
hepatoma (4 papers, 2020 to 2023). "Upregulation of COX5B gene transcripts in hepatoma cells is also associated with an unfavorable postoperative prognosis of HCC, concurring with increased proliferation and migration of this tumor type." (PMID 37894381, 2023). "In addressing the role of COX5B in hepatoma, the loss- and gain-of-function experiments for COX5B were conducted." (PMID 32580279, 2020). "In which, COX5B was highly expressed in hepatoma and associated with unfavorable postoperative prognosis." (PMID 32580279, 2020). "Consequently, COX5B expression was associated with increased hepatoma cell proliferation, migration and xenograft growth." (PMID 32580279, 2020). "Bioenergetic alteration-dependent activation of AMPK was found to occur in hepatoma cells via COX5B regulation of UHMK1 expression." (PMID 36551283, 2022). "Consistently, the reduced level of Snail, the classical marker for cell migration, also supported that silencing COX5B in hepatoma restrained cell migration." (PMID 32580279, 2020). "The COX5B-mediated regulatory event on UHMK1 expression was subsequently demonstrated as bioenergetic alteration-dependent activation of AMPK in hepatoma cells." (PMID 32580279, 2020). "Experimental alterations of COX5B levels revealed that it indeed exhibited a growth-promoting effect, enhancing hepatoma cells proliferation and migration." (PMID 32580279, 2020). "In silico-based and clinical tissue-based experiments, aiming at identification of potential bioenergy modulators controlling hepatoma progression, revealed COX5B." (PMID 32580279, 2020). "The mRNA and protein levels of UHMK1 and ULK1 were then examined for validation by using samples from COX5B downregulated or overexpressed hepatoma cells." (PMID 32580279, 2020). "In contrast, overexpressing COX5B markedly elevated cell proliferative rates in these hepatoma cell lines, suggesting that COX5B expression enhanced cell proliferation in hepatoma cells." (PMID 32580279, 2020). "It was discovered that knock-down of COX5B significantly repressed cell migration, while increasing its expression enhanced cell migration in hepatoma cell lines." (PMID 32580279, 2020). "Finally, one report has indicated that COX5B regulates tumor growth by modulating the AMPK-UHMK1-ERK signaling cascade in hepatoma." (PMID 35359403, 2022). "However, only COX5B revealed a borderline correlation with the clinical outcome, suggesting a trend of growth promoting function in hepatoma." (PMID 32580279, 2020). "Similarly, the migratory ability was also rescued by elevating UHMK1 expression in hepatoma cells under COX5B depletion." (PMID 32580279, 2020). "Clinical correlation studies showed that COX5B likely served as a growth-promoting gene and could be used as a predictor for clinical outcomes in hepatoma patients." (PMID 32580279, 2020). "Additionally, the results of xenograft experiments were in agreement with the notion that reduced COX5B expression impeded tumorigenesis in hepatoma." (PMID 32580279, 2020). "In summary, in the present study, the oncogenic role of COX5B in hepatoma was demonstrated." (PMID 32580279, 2020). "Taken together, although COX5B silencing-mediated ATP deficiency could cause other kinds of cell stress, our experimental evidences indicated that the AMPK-UHMK1-ERK/Stathmin cascade constituted a great part in the molecular events so as to inhibit hepatoma cell growth." (PMID 32580279, 2020). "Next, to determine whether the relationship between COX5B and UHMK1 could also be observed in samples from patients with hepatoma, the western blot and qRT-PCR were conducted." (PMID 32580279, 2020). "There were 6 distinct hepatoma cell lines, including J7, SK-Hep1, Mahlavu, Huh7, Alexander and HepG2, utilized in this experiment, comparing between cells with and without COX5B knockdown." (PMID 32580279, 2020).
hepatoma (continued). "However, in this study, silencing COX5B in hepatoma cells was not sufficient to shift the bioenergy-producing origin to glycolysis, except for Huh7 cells, despite it indeed resulted in reduced OXPHOS activity." (PMID 32580279, 2020). "Next, to examine whether UHMK1 indeed served as a downstream effector of COX5B in modulating hepatoma progression, the rescue experiment was conducted by overexpressing UHMK1 in cells with or without siRNA knockdown of COX5B." (PMID 32580279, 2020).
Parkinson disease (4 papers, 2011 to 2021). A progressive degenerative disorder of the central nervous system characterized by loss of dopamine producing neurons in the substantia nigra and the presence of Lewy bodies in the substantia nigra and locus coeruleus. "Second, and more interesting, the oxidative phosphorylation chain, including seven genes (ATP5C1, ATP6AP1, ATP6V1H, COX5B, COX6B1, NDUFA1, and UQCRC1), five of them shared with Huntington's and Parkinson's disease KEGG categories." (PMID 21541025, 2011).
gastric cancer (3 papers, 2020 to 2021). A primary or metastatic malignant neoplasm involving the stomach. "In this study, we found that knockdown of gastrin in gastric cancer cells could result in the overexpression of COX17, COX5B, and ATP5J proteins, elevation of mitochondrial membrane potential, and reduction of ROS production in gastric cancer cells." (PMID 33937399, 2021).
Hypertension (3 papers, 2019 to 2024). The presence of chronic increased pressure in the systemic arterial system. "Similarly, proteins important for LV structure (MYL3), and mitochondrial function (COX5B), were up-regulated and down-regulated, respectively, in human hypertension." (PMID 38879891, 2024). "Here, in the myocardium of the hypertension-induced HFpEF, we also observed the increased expression of PGC-1a after CANA treatment, which was consistent with the increased expression of the mitochondrial membrane respiratory chain component protein subunit Ndufb4, COX2, Cox4i1, Cox5b, and Cox6a1." (PMID 35370704, 2022).
depression (2 papers, 2020 to 2024). "But even more importantly, Cox5b is a candidate hippocampal biomarker of susceptibility and resilience to stress in a rat model of depression." (PMID 32670347, 2020).
mesothelioma (2 papers, 2023 to 2025). A usually malignant and aggressive neoplasm of the mesothelium which is often associated with exposure to asbestos. "Other highly expressed genes in sarcomatoid mesothelioma cell lines were two ATP synthase subunits (ATP5H, ATPO), MTCO2, COX5B, COX 6C2, IDH3A, IDH3B and TIMM9." (PMID 37297007, 2023).
non-small cell lung carcinoma (2 papers, 2021 to 2025). A group of at least three distinct histological types of lung cancer, including non-small cell squamous cell carcinoma, adenocarcinoma, and large cell carcinoma. "Differential expression of COX5b subunit has been reported in colorectal carcinomas, and knockdown of the COX5a subunit by siRNA has been shown to reduce non-small cell lung cancer (NSCLC) cell migration and invasion." (PMID 34262651, 2021). "Heat shock protein family D member 1 (HSPD1) promoted the progression of non-small cell lung cancer (NSCLC) dependent on SLC6A8 and COX5B." (PMID 41502520, 2025).
Obesity (2 papers, 2020 to 2024). Accumulation of substantial excess body fat. "pTSL@(P+I) effectively upregulates UCP1 and COX5B expression by activating the transcription axis of PPARγ/PGC1α and HSF1/PGC1α, thereby promoting white adipose tissue browning and reducing obesity." (PMID 39195401, 2024). "This nanocomplex effectively upregulates UCP1 and COX5B expression by activating the transcription axis of PPARγ/PGC1α and HSF1/PGC1α, thereby promoting white adipose tissue browning and improving obesity." (PMID 39195401, 2024). "Compared with the obesity group, the expression of ARG2, COX5B, and ZNT1 in the ZnSO4-treated group was significantly decreased, while the expression of LYAR and TM165 was significantly increased." (PMID 32462040, 2020).
ovarian carcinoma (2 papers, 2021 to 2025). A malignant neoplasm originating from the surface ovarian epithelium. "The results revealed that COX5B was significantly elevated in ovarian cancer, UCEC and lung cancer compared to normal tissues." (PMID 41502520, 2025). "Oncoprint profile of CYCS, VEGFA, IL6, UQCRC1, UQCRFS1, COX5B, ACKR3/CXCR7, and FYN indicated that these genes were either amplified or overexpressed in 4–25% of the ovarian cancer patients." (PMID 34439877, 2021). "The identification of CYCS, VEGFA, IL6, UQCRC1, UQCRFS1, COX5B, ACKR3/CXCR7, and FYN as pro-tumorigenic nodes designates them as the novel and potentially druggable targets for effective targeted adjuvant therapy for ovarian cancer." (PMID 34439877, 2021).
prostate carcinoma (2 papers, 2015 to 2024). A carcinoma that arises from epithelial cells of the prostate gland. "Earlier studies have demonstrated that elevated levels of COX5B in human breast and prostate cancer tissues enhance the proliferative and invasive capabilities of cancer cells." (PMID 39586785, 2024). "Coincidentally, COX5B upregulation was also reported in prostate cancer and cutaneous squamous cell carcinoma." (PMID 26506233, 2015).
Sepsis (2 papers, 2017 to 2021). Sepsis is defined as life-threatening organ dysfunction caused by a dysregulated host response to infection. "COX5B could be a promising biomarker candidate since a significant association was found during experimental sepsis in the present study." (PMID 28246552, 2017). "COX5b also seems to undergo a possible downregulation from intermediate to late sepsis and was confirmed by the Western Blot analysis." (PMID 28246552, 2017). "For future research, COX5B should be evaluated as a biomarker in both human urine and serum to identify sepsis." (PMID 28246552, 2017). "Corresponding to the SDS gel analysis, Western Blot analysis also showed a decreased expression of COX5B at 48 hours after sepsis." (PMID 28246552, 2017). "In the other spot overpresent in 24 h sepsis, ID 2494, cytochrome c oxidase subunit B (“COX5B”) was recognized." (PMID 28246552, 2017). "The protein spot ID2494 (COX5B) was found in the previous 2D DIGE experiment to be significantly lower expressed in the sample sepsis 48 h treatment compared to the samples sepsis 24 h treatment and control." (PMID 28246552, 2017). "During the course of sepsis, COX5B was found to be less expressed by both MALDI-TOF and Western Blot analysis in the late phase (i.e., after 48 hours) as compared to the early phase of sepsis." (PMID 28246552, 2017). "Although this study did not analyze proteome alterations during sepsis and in piglets, it showed the importance of COX5B in the kidney." (PMID 28246552, 2017). "Although sepsis-AKI led to reduced mtDNA levels and integrity, it did not affect mRNA expression of mitochondrial genes encoding key components of the mitochondrial electron transport chain complexes (i.e., ND1, ND4, COX1, CYTB, COX5b and NDUFA1)." (PMID 33494815, 2021).